KRAS (KRas proto-oncogene, GTPase)
Diseases named in the same sentence as KRAS in open-access papers (continued):
Sharing a sentence is not in itself a finding about the gene and the disease.
colorectal cancer (continued). "Already this has been described in a small cohort of patients with colorectal cancer initially demonstrating KRAS wild-type tumors, which subsequently were noted to have molecular alterations (via serum analysis) including KRAS, NRAS, EGFR, and BRAF after treatment with anti-EGFR therapies." (PMID 28030802, 2017). "CircRNAs serving as promising colorectal cancer biomarkers may improve the positive detection rate of KRAS, which assists in predicting or diagnosing colorectal cancer." (PMID 28535767, 2017). "Moreover, the presence of activating mutations of KRAS, NRAS, and BRAF genes, as well as amplification of MET and HER2 genes in these colorectal cancers are reliable predictors of tumor resistance to GEF therapy." (PMID 26461472, 2017). "Median PFS/OS was 1.4/7.1 months in the BRAF-mutant colorectal cancer cohort, 1.5/4.7 months in the KRAS-mutant colorectal cancer 45 mg dose cohort, 3.5/9.1 months in the KRAS-mutant colorectal cancer 60 mg dose cohort, and 2.1/4.8 months in the biliary cohort." (PMID 28152546, 2017). "It was later found out that EGFR expression by IHC in colorectal cancer did not correlate with response to therapy, and subsequent investigation led to the identification of the KRAS mutation conferring resistance." (PMID 28030802, 2017). "The DNA corresponding to parallel PBF- and GAF-fixed samples of 8 colorectal cancer cases (6 KRAS codon 12 mutant and 2 KRAS codon 117 and 146 mutant according to the previous test) were then subjected to direct sequencing, pyrosequencing and Sequenom MassARRAY®." (PMID 28796828, 2017). "The detection of KRAS and BRAF mutations is a crucial step for the correct therapeuticapproach and predicting the epidermal growth factor receptor (EGFR)-targeted therapyresistance of colorectal carcinomas." (PMID 28580315, 2017). "Activating mutations in KRAS have been described in various cancer types including non-small cell lung and pancreatic cancers and in around 50% of colorectal carcinomas." (PMID 28806777, 2017). "The samples were specifically selected for this study; hence the mutational rates in the current sample set are not representative for the incidence of KRAS mutations in the general colorectal cancer patient population." (PMID 27685259, 2016). "We describe a novel antitumoral mechanism of vitamin C in KRAS mutant colorectal cancer that involves the Warburg metabolic disruption through downregulation of key metabolic checkpoints in KRAS mutant cancer cells and tumors without killing human immortalized colonocytes." (PMID 27323830, 2016). "Metabolomics revealed that vitamin C causes pentose phosphate pathway metabolites and glycolytic intermediates located up-stream of glyceraldehyde 3-phosphate dehydrogenase (GAPDH) to increase in KRAS and BRAF mutated colorectal cancer cells, whereas metabolites down-stream of GAPDH were decreased." (PMID 27616976, 2016). "The IdyllaTM KRAS Mutation Assay is not intended to identify the rare mutations G12F, G13C, or G13R (<0.5% prevalence in colorectal cancer), which were previously detected in 6 archival FFPE samples by routine reference methods." (PMID 27685259, 2016). "In addition, we also investigated critical molecular events such as KRAS, BRAF and PIK3CA mutations and MSI status, all of which have been associated with colorectal cancer prognosis in order to adjusted our results." (PMID 26515606, 2016). "Recent data indicate that the cfDNA in plasma could represent a new sample type for the analysis of KRAS mutations in tumors and act as a potential biomarker for anti-EGFR therapy efficacy in colorectal cancer." (PMID 27519791, 2016).
colorectal cancer (continued). "MiR-143 expression was found to target KRAS mRNA and to be down-regulated in colorectal cancer." (PMID 26646588, 2016). "The progression of colorectal cancer (CRC) involves recurrent amplifications/mutations in the epidermal growth factor receptor (EGFR) and downstream signal transducers of the Ras pathway, KRAS and BRAF." (PMID 27562229, 2016). "The overall concordance between the IdyllaTM KRAS Mutation Assay and the confirmed reference routine test results for colorectal cancer samples was found to be 98.9%, with a negative percent agreement of 99.25% and a positive percent agreement of 98.68%." (PMID 27685259, 2016). "For example, in patients with metastatic KRAS wild-type colorectal cancer treated with an anti-EGFR antibody, blood analyses showed that the appearance of KRAS mutants, conferring resistance against anti-EGFR antibodies, preceded progressive disease with up to 10 months." (PMID 27270325, 2016). "In conclusion, miR-450b-5p induced by oncogenic KRAS is required for colorectal cancer progression." (PMID 27494869, 2016). "We found that colorectal cancer cells survived under the condition of glucose depletion, and their resistance to such conditions depended on genomic alterations rather than on KRAS mutation alone." (PMID 27924922, 2016). "KRAS plays a significant role in the etiology and progression of colorectal cancer (CRC), but the mechanism underlying this process has not been fully elucidated." (PMID 27857191, 2016). "Considering that KRAS mutations may also confer resistance to EGFR inhibitors, patients who have colorectal cancer with KRAS mutation could receive more tailored management." (PMID 27120810, 2016). "The present study showed that the metabolism of colorectal cancer, distinct from that of pancreatic cancer, depended on genomic alterations, which previously have been uncharacterized and was not restricted to KRAS mutation alone." (PMID 27924922, 2016). "The KRAS, NRAS and BRAF mutations in colorectal cancer are normally mutually exclusive." (PMID 26968814, 2016). "Importantly, for colorectal cancer cetuximab is only effective for tumors expressing wild-type KRAS, as mutant KRAS provides growth signals that bypass EGFR inhibition." (PMID 27669306, 2016). "Moreover, KRAS and NRAS genes mutation limits effectiveness of monoclonal antibodies against EGFR (cetuximab, panitumumab) in colorectal cancer patients." (PMID 25902737, 2016). "Six of the 12 specimens displayed G13C, G12F, or G13R KRAS exon 2 mutations, which are not included in the IdyllaTM KRAS Mutation Assay because they are rarely observed (<0.5%) in the large colorectal cancer cohorts published." (PMID 27685259, 2016). "In conclusion, we found that the metabolism of colorectal cancer, which is different from that of pancreatic cancer, depended on genomic alterations that are uncharacterized and not restricted to KRAS mutation alone." (PMID 27924922, 2016). "Our data suggests that COTI-2 is effective against colorectal cancer cell lines regardless of their KRAS mutation status." (PMID 27150056, 2016). "The use of anti-EGFR monoclonal antibodies (mAb anti-EGFRs) in colorectal cancer has shown that KRAS and NRAS represent the main resistance mechanisms to this type of treatment and are thus used in clinical practice to select the patients who should not be treated with anti-EGFR therapy." (PMID 27886225, 2016).
colorectal cancer (continued). "However, immunohistochemical assessment of EGFR expression has not been a good predictor of response to the EGFR antibodies cetuximab or panitumumab in colorectal cancer, compared with EGFR copy number and KRAS mutation analysis." (PMID 27070783, 2016). "Nevertheless, the ratio between LC3II and LC3I protein levels increases in the presence of KRAS oncogene, which further results in p62 downregulation, indicating an induction of the autophagic process, as shown in the current study utilizing colorectal cancer cells." (PMID 26802026, 2016). "In metastasized KRAS wild type colorectal carcinomas, an ICER of €112,707 per QALY was reported." (PMID 27100871, 2016). "Furthermore, a patient with a BRAF V600E-mutant, wt KRAS colorectal cancer, with a history of early progression to cetuximab-based therapy, was found to have a KRAS G12D mutation (24.39%) in cfDNA instead, which was not previously detected in the tumor tissue." (PMID 25980577, 2015). "In conclusion, the RALA pathway impinges on the transcription of a distinct subset of target genes in colorectal cancer cells independent of the KRAS and BRAF mutational status." (PMID 26033452, 2015). "Our previous reports have also demonstrated that KRAS codon 12 mutation, but not codon 13 mutation, is associated with more positive lymph nodes and higher pTNM stages in colorectal cancer." (PMID 26530529, 2015). "KRAS mutational status is considered a negative predictive marker of the response to anti-EGFR therapies in colorectal cancer (CRC) patients." (PMID 26110767, 2015). "The FDA acknowledged the evidence base for KRAS presence as a marker for patients who would achieve no benefit from anti-EGFR therapy and issued a label update for the entire class of drugs, recommending KRAS testing as part of colorectal cancer patient management." (PMID 26858745, 2015). "To optimize the λ value to determine the mutant detection criteria, we used 20 colorectal cancer FFPE samples (10 KRAS exon 2 mutation-positive and 10 mutation-negative samples)." (PMID 25954997, 2015). "Approximately 20% of all colorectal cancers contain wild KRAS (the absence of a mutation on the KRAS oncogene) and only tumours which express the wild-type KRAS can be candidates for cetuximab, while the patients with mutant KRAS are considered resistant." (PMID 26557880, 2015). "Retrospective‐prospective approaches have been a mainstay approach, for example with KRAS (and now NRAS) mutations demonstrating lack of benefit of anti‐EGFR monoclonal antibody therapies in colorectal cancer." (PMID 25557400, 2015). "While KRAS MT status is clearly associated with lack of response to the anti-EGFR antibody cetuximab in colorectal cancer, in lung adenocarcinoma KRAS MT status does not appear to predict response to this agent." (PMID 26471290, 2015). "Although molecular biology remains the reference method for detecting KRAS mutation, immunohistochemistry could be an attractive method for detecting BRAF V600E mutation in colorectal cancer." (PMID 25983749, 2015). "Mutations in KRAS and BRAF genes seem to occur in a mutually exclusive manner, and both are suggested as integral components for an effective molecular classification of colorectal cancer." (PMID 25929517, 2015). "Unlike KRAS mutations, which constitute a large percentage of the mutations in colorectal cancer, NRAS mutations are rare." (PMID 26691448, 2015). "Recent data show that apart from KRAS and BRAF mutations, mutations in genes related to colorectal cancer stem cells or cells that undergo EMT, such as CD133 and PLS3, might have therapy-predictive value and clinical significance." (PMID 25902072, 2015).
colorectal cancer (continued). "Furthermore, two pilot studies in advanced colorectal cancer patients with wtKRAS demonstrated emerging KRAS aberrations in cfDNA during treatment with an anti-EGFR therapy." (PMID 25980577, 2015). "With respect to cetuximab for the treatment of colorectal cancer, the negative prognostic value of KRAS mutations is rigorously defined and is similar to the lack of a response to erlotinib in KRAS-mutant patients with NSCLC." (PMID 25962919, 2015). "In addition, we also investigated critical molecular events such as APC, KRAS, BRAF and PIK3CA mutations and MSI, all of which have been associated with colorectal cancer prognosis to justify the prognostic role of NEAT1." (PMID 26314847, 2015). "In addition, we also investigated critical molecular events such as KRAS, BRAF and PIK3CA mutations and MSI, all of which have been associated with colorectal cancer prognosis to justify the independent prognostic role of NDRG4." (PMID 25749388, 2015). "KRAS mutation testing has become mandatory prior to the administration of therapy with the anti-EGFR antibodies, cetuximab or panitumumab, for patients with advanced colorectal cancer." (PMID 25674493, 2015). "Data of the Kirsten Ras in Colorectal Cancer Collaborative Group Studies (RASCAL I) suggested that the risk of recurrence and death is increased by the presence of KRAS mutations, and the updated RASCAL II study confined the correlation of KRAS mutation and survival prognosis to the G12V mutation." (PMID 25742883, 2015). "In NSCLC, these markers, similar to the use of KRAS mutations in colorectal cancer, have reproducibly associated with absence of benefit from EGFRi therapy." (PMID 24386952, 2014). "For example, standard treatment guidelines recommend KRAS and NRAS testing for colorectal cancer patients and that patients with KRAS- and NRAS-mutated colorectal cancer not be treated with epidermal growth factor receptor inhibitors such as cetuximab and panitumumab." (PMID 25593991, 2014). "However, the beneficial effects of these MADs are restricted to colorectal cancer patients which were diagnosed with unmutated KRAS gene in their cancers." (PMID 29147386, 2014). "Statins may inhibit the expression of the mutant KRAS phenotype by preventing the prenylation of the KRAS protein and normalize the phenotype into KRAS wild type and therefore render KRAS mutant colorectal cancers sensitive to EGFR antibodies." (PMID 25375154, 2014). "Through clinical trials, several groups have observed that colorectal cancer patients without somatic mutations in KRAS benefit from anti-EGFR therapy relative to patients harboring a somatic KRAS mutation 4–8." (PMID 24890702, 2014). "This is similar to Grivennikov and colleagues who report an upregulation of IL-23 in early cancers but no further increase in expression in more advanced mouse colorectal cancers caused by Apc loss and forced KRAS or BRAF activation." (PMID 25015728, 2014). "It is now well established that KRAS mutations are the main reason for resistance to anti-epidermal growth factor receptor (EGFR) antibodies, and account for nearly two-thirds of EGFR downstream effector alterations in colorectal cancer." (PMID 25491325, 2014). "Our findings thus support the notion that DbαEGFR-scTRAIL therapy in combination with apoptosis-sensitizing agents may be promising for the treatment of EGFR-positive colorectal cancers, independently of their KRAS status." (PMID 25198428, 2014). "Despite the revolu¬tion that occurred in the field of molecular marker research, only Serum CEA, Immunohistochemical analysis of mismatch repair proteins and PCR testing for KRAS and BRAF mutations have confirmed their clinical utility in the management of colorectal cancer." (PMID 24653752, 2014). "Occurrence of concomitant KRAS mutations was more frequently seen in colorectal cancer patients with FBXW7 mutations in comparison to non-colorectal group." (PMID 24586741, 2014).
colorectal cancer (continued). "For instance, it has been suggested that not all KRAS mutations in colorectal cancer are equally effective in conferring resistance to anti-EGFR antibodies." (PMID 24964744, 2014). "The 5-year colorectal cancer-specific survival probabilities were 80.6% for cases with KRAS-wild-type/BRAF-wild-type tumors, 67.9% for cases with codon 12 mutations, 75.8% for cases with codon 13 mutations, 79.4% for cases with codon 61 mutations, and 76.7% for cases with codon 146 mutations." (PMID 24885062, 2014). "The purpose of this research was to improve Activating KRAS Detection Chip by using a weighted enzymatic chip array (WEnCA) platform to detect activated KRAS mutations status in the peripheral blood of non-small-cell lung cancer (NSCLC) and colorectal cancer (CRC) patients in Taiwan." (PMID 24884535, 2014). "Previous studies suggest that KRAS codon 61 and 146 mutations may also predict resistance to anti-EGFR therapy in colorectal cancer." (PMID 24885062, 2014). "KRAS mutations were observed in 43% of ovarian carcinomas and in 30% of colorectal carcinomas, which do not contribute to differential diagnosis in mucinous neoplasms of the colon and ovary." (PMID 25297496, 2014). "In colorectal cancer, the demonstration that patients with KRAS mutated tumors did not benefit from anti-EGFR monoclonal antibodies was established independently of the technology used to identify KRAS mutated tumors." (PMID 23935912, 2013). "In addition to KRAS mutation, genetic alterations in NRAS, HRAS, BRAF, and RAF1 were found in colorectal cancer samples analyzed in this study." (PMID 23700467, 2013). "As one of the RAS family, NRAS shared close relations with KRAS, while unlike KRAS mutation occupies such a large percentage in colorectal cancer, NRAS mutations were rare." (PMID 24339949, 2013). "In advanced colorectal cancer patients with mutated KRAS, for example, targeted therapies have provided no benefit showing a clear need to establish new therapeutic strategies." (PMID 24279335, 2013). "KRAS, BRAF and PIK3CA mutations are frequently observed in colorectal cancer (CRC)." (PMID 23671647, 2013). "Our data confirm that the sensitivity of PIK3CA mutant colorectal cancer to PI3K/mTOR inhibitors may depend on the presence of wild-type KRAS gene." (PMID 23826249, 2013). "KRAS, BRAF and PIK3CA mutations are commonly found in colorectal cancers." (PMID 23617638, 2013). "Unlike in colorectal cancer however, where KRAS mutations have been described in 34-42% of all tumors, KRAS mutations in melanoma are rarely observed." (PMID 24244691, 2013). "Colorectal cancer is generally considered to progress from adenoma to carcinoma, with APC and KRAS mutations occurring early; APC mutations in the normal epithelium and KRAS somewhere along the transition from small to medium size adenoma." (PMID 24066160, 2013). "In summary, our data make sense in light of five recent studies, which demonstrated that KRAS codon 13 mutations, but not codon 12 mutations, conferred benefit from cetuximab therapy in advanced colorectal cancer." (PMID 23437064, 2013). "In colorectal cancer, the presence of mutations in the KRAS gene indicates that the tumor will not respond to EGFR antibody therapy." (PMID 24280411, 2013). "The logic of using a downstream inhibitor to block the consequences of an otherwise undruggable upstream gene defect is thus supported, reinforcing lessons learned from constitutive KRAS-mutant-activated colorectal cancer in which upstream RAS-ERK blockade by EGFR antibodies is ineffective." (PMID 24377088, 2013). "The clinical benefit of this targeted therapy is restricted to wild-type KRAS colorectal carcinoma." (PMID 23785428, 2013). "For example, anti-epidermal growth factor receptor antibodies should not be administered to colorectal carcinoma patients with KRAS mutations in codons 12 or 13, although improved cost-effectiveness can be demonstrated for the remaining subset of patients." (PMID 23706012, 2013).